CKS2 (CDC28 protein kinase regulatory subunit 2)
Diseases named in the same sentence as CKS2 in open-access papers (continued):
Sharing a sentence is not in itself a finding about the gene and the disease.
cancer (continued). "Although CKS2 has been characterized as an oncogene in many human cancers, its role in CC is not clear and its potential mechanism is mainly unexplored." (PMID 39548421, 2024). "In contrast, immunostaining of CKS2 exhibited negative or low reactivity in non-cancer cervix tissues." (PMID 35935749, 2022). "CKS2 and CORO1C participate in the growth, invasion, and prognosis of several types of cancers." (PMID 33968720, 2021). "Although CKS2 has been shown to play an important role in many types of cancer, its function in PDAC has not been reported." (PMID 29764514, 2018). "CKS2 (chr9q22.2), CEP55(chr10q23.33), UHRF1 (chr19p13.3), RRM2 (chr2p25.1), AURKA (chr20q13.2), FLJ39632 (chr14q11.2), FAM83D (chr20q11.23), NEK2 (chr1q32.3) and MAD2L (chr4q27) were all located on PCSRs and showed over-expression in the 9, 8, 10, 9, 8, 9, 9, 8 and 9 types of cancers, respectively." (PMID 24796549, 2014). "The pathway in cancer (KEGGID: 05200) was the top core pathway, and one gene in this pathway, CKS2, has been shown to be overexpressed in PDAC relative to normal tissue." (PMID 29764514, 2018).
CKS2 also shares sentences with these, for which no sentence is quoted: non-small cell lung carcinoma (3 papers); adrenocortical carcinoma (2); bladder urothelial carcinoma (2); colon adenocarcinoma (2); head and neck squamous cell carcinoma (2); lymphoma (2); ovarian carcinoma (2); prostate adenocarcinoma (2); small cell lung carcinoma (2); anaplastic oligodendroglioma (1); central neurocytoma (1); digestive system tumors (1); Ductal carcinomas (1); dysplasia (1); endometriosis (1); gastric adenocarcinoma (1); glaucoma (1); Glioblastoma Multiforme (1); laryngeal squamous cell carcinoma (1); melanoma (1); oligodendroglioma (1); pancreatic adenocarcinoma (1); pilocytic astrocytoma (1); pleomorphic xanthoastrocytoma (1); prostate tumor (1); psoriasis (1); renal cell carcinoma (1); reproductive system neoplasm (1); rheumatoid arthritis (1); serous ovarian carcinoma (1).
A further 4 diseases each share a sentence with CKS2 in 1 paper.